Y_RNA (Y RNA )
Gene: Miscellaneous RNA gene on chromosome 10 (130,505,106 to 130,505,201, forward strand). Ensembl gene ENSG00000222997.
Homologues: Orthologues: chimpanzee Y_RNA (99% identical). Paralogues in human: Y_RNA (82% identical), RNY4 (81% identical), RNY4P24 (81% identical), RNY4P3 (81% identical), Y_RNA (81% identical), RNY4P13 (80% identical), RNY4P7 (80% identical), Y_RNA (80% identical), RNY4P10 (79% identical), RNY4P14 (79% identical), RNY4P17 (79% identical), RNY4P34 (79% identical), and 89 more.